TTR (transthyretin)
Diseases named in the same sentence as TTR in open-access papers (continued):
Sharing a sentence is not in itself a finding about the gene and the disease.
ovarian carcinoma (continued). "While TF alone may have limited diagnostic value, its effectiveness improves when combined with other markers such as CA‐125, apolipoprotein A‐I, and transthyretin for early ovarian cancer detection." (PMID 40927964, 2025). "In this study, data from previous studies showed that the cutoff level for TTR values was 22.8 mg/dL for gastric cancer, an average of 180.12±50.16 (mg/L) for lung cancer, and an average of 14.9±9.7 mg/dL for ovarian cancer, which were higher than the data in this study." (PMID 40777143, 2025). "Similarly, a new ovarian cancer biomarker is transthyretin (TTR) and serum human epididymis protein 4 (HE4)." (PMID 35557858, 2022). "In 2009, the Food and Drug Administration approved the clinical use of OVA-1, a serum test analyzing five biomarkers: CA-125, II-microglobulin (both elevated in ovarian cancer), apolipoprotein A1, prealbumin (transthyretin), and transferrin (which are decreased in ovarian cancer)." (PMID 28448435, 2017). "Transthyretin has been used as a biomarker for malnutritional status and inflammation, acute and chronic diseases, but post-translational modified forms have also been reported as part of a biomarker panel for early detection of ovarian cancer." (PMID 22970327, 2012). "Recently, a truncated variant of transthyretin together with apolipoprotein A1 and a connective tissue activating protein III were described as an efficient panel of new biomarkers for detecting early stage epithelial ovarian cancer in women." (PMID 22970327, 2012). "Finally, our data also suggest that apoA-I, TTR, and TF, when analyzed collectively, are unique to ovarian cancer and thus provide for the first time a disease-specific multiple marker panel for the early detection of OC." (PMID 19662218, 2007). "TTR levels have been reported to be inversely correlated to tumor volume in ovarian cancer." (PMID 19662218, 2007). "Our results suggest that the differential expression pattern of isoforms of Hp alpha and the conserved expression profile of Transthyretin might correspond to a signature for each patient, and whose pattern could be representative of the ovarian cancer ascitic fluid stage." (PMID 24576319, 2014). "Combining transthyretin (TTR) with CA125, hemoglobin, apolipoprotein AI, and transferrin improved the detection of early-stage ovarian cancer compared to CA125." (PMID 38275400, 2024). "The combination of transthyretin and apolipoprotein A1 with CA125 improved both the sensitivity and specificity of ovarian cancer diagnosis compared with the sensitivity and specificity of the individual biomarkers determined separately." (PMID 37238197, 2023). "APOA1 is also part of the OVA1 test for ovarian cancer which utilizes APOA1, transthyretin, transferin, CA-125 and β2-microglobulin as the panel biomarkers." (PMID 26463353, 2016). "Different expressions of TTR in the sera have been reported in SARS, dengue fever, ovarian cancer, malignant melanoma, HCC related to HBV, and in CSF in some neurological disorders such as Alzheimer, Parkinson, and schizophrenia." (PMID 24497876, 2014). "Differential expressions of TTR in the sera have been reported in SARS, dengue fever, ovarian cancer, malignant melanoma, and in the cerebrospinal fluid of some neurological disorders such as Alzheimer's, Parkinson, and schizophrenia." (PMID 24066001, 2013). "The new combination of transthyretin, and apolipoprotein A1 with CA125 improved both the sensitivity and the specificity of ovarian cancer diagnosis compared with those of individual biomarkers." (PMID 22970327, 2012). "The present study showed the significant improvement of sensitivity for the diagnosis of ovarian cancer when using a combination of three serum biomarkers, including CA125, transthyretin, and apolipoprotein A1, using a multiplex liquid assay system." (PMID 22970327, 2012).
ovarian carcinoma (continued). "Three serum biomarkers, ApolipoproteinA-I, Transthyretin and Transferrin, combine with CA125 can be used to significantly improve detection of early stage ovarian cancer over CA125 alone." (PMID 19662218, 2007). "Among more than fifteen ovarian cancer‐related biomarkers identified to date, the most widely studied include CA‐125, HE4, kallikreins, prostasin (PSN), transthyretin (TTR), transferrin, vascular endothelial growth factor (VEGF), apolipoprotein A‐I (ApoA‐I), and osteopontin (OPN)." (PMID 40927964, 2025). "In addition, the combination of TTR and APOA1 with MUC16 and TF has shown a 96% overall sensitivity for early detection of ovarian cancer." (PMID 40836974, 2024). "However, the clinical development of TTR, B2M and APOA1 as biomarkers for ovarian cancer is still ongoing." (PMID 40836974, 2024). "Using immunological procedures we were recently able to show the presence of TTR in ascitic fluid from women with ovarian cancer, however no quantitative data, especially with regard to cancer stages, is as yet available." (PMID 16225703, 2005). "Notably, OVA1® is a United States (US) Food and Drug Administration (FDA) approved test, which includes apolipoprotein A-I (APOA1), transthyretin (TTR), transferrin (TF), β2-microglobulin (B2M), along with MUC16, and has demonstrated effectiveness in detecting early-stage ovarian cancer." (PMID 40836974, 2024). "But, the four-biomarker panel (CA125 plus transthyretin plus apolipoprotein A1 plus hemoglobin) did not improve the overall sensitivity and specificity for discriminating between ovarian cancer and healthy individuals (and/or benign group) as compared to the three-biomarker panel in the ROC curve." (PMID 22970327, 2012). "In conclusion, we have shown that ApoA-I, TF, and TTR, in combination with CA125 in a multivariate predictive model, have the potential to improve the specificity and sensitivity for the early detection of ovarian cancer over CA125 alone, particularly for the mucinous histopathologic subtype." (PMID 19662218, 2007). "When ApoA1 was combined with CA125 and TTR, not only was a significant improvement observed in the overall sensitivity and specificity, but the panel was also sufficient for maximum discrimination between noncancer, stage I–II and all stages (I–IV) of ovarian cancer." (PMID 33800113, 2021).
diabetes (33 papers, 2010 to 2025). "As previously reported, TTR should be correlated with diabetes-associated diseases, e.g., type I diabetes patients showed lower serum TTR levels." (PMID 31847264, 2019). "Retinol binding protein 4 (RBP4), a protein secreted by adipocytes and bound in plasma to transthyretin (TTR), has been associated with obesity, the early phase of insulin resistance, metabolic syndrome, and type 2 diabetes mellitus." (PMID 29747616, 2018). "We also found that TTR was related to obesity and further validated its elevation in patients with obesity (overweight), indicating that this protein is closely associated with obesity and diabetes." (PMID 31504048, 2019). "Deficiency of the normal function of TTR has been known to be associated with obesity and diabetes." (PMID 30733681, 2019). "Another interesting diabetes-associated marker found in this study is transthyrethin (TTR)." (PMID 25415563, 2014). "Targeted MRM analysis revealed differences in several proteins, which could be divided in diabetes-associated (fibrinogen, transthyretin), obesity-associated (complement C3), and diet-associated markers (apolipoproteins, especially apolipoprotein A-IV)." (PMID 25415563, 2014). "Our study also revealed that TTR and GC may also serve as potential early diagnostic markers of diabetes-related cataracts and other eye complications, providing a direction for further research on these diseases and a theoretical basis for diagnosis, prevention, and treatment targets." (PMID 37884923, 2023). "The Western blot results showed that the expression of TTR was significantly increased in the diabetes group as compared to the control while GC was significantly downregulated." (PMID 37884923, 2023). "In obese patients, an increase was observed in TTR expression, suggesting it as a biomarker for diabetes progression in overweight patients." (PMID 35897655, 2022). "Unfortunately, Refai and colleagues discovered that serum transthyretin tetramer concentration was decreased, whereas the monomeric form was increased in patients with type 1 diabetes mellitus." (PMID 35889910, 2022). "In terms of comorbidities, hypertension, diabetes and atrial fibrillation were highly prevalent in TTR‐CA‐diagnosed patients, as well as in those with an implanted pacemaker." (PMID 34390490, 2021). "Studies aiming to establish correlations between TTR and glucose blood levels, both in patients with diabetes and in healthy controls, can also shed light on this topic." (PMID 34199897, 2021). "An association between increased levels of both RBP4 and TTR and an elevated risk of insulin resistance (the precursor state to T2DM) and CVD (the macrovascular complication of diabetes) has been reported in several studies." (PMID 29747616, 2018). "TTR is decreased in type 1 diabetes mellitus, yet is highly abundant in PC juice, because the pancreatic islet is destroyed, allowing proteins to leak into the pancreatic ductal system." (PMID 29190982, 2017). "On the other hand, in the pharmaceutical industry, health benefits are sought in various diseases such as cancer, stress, antisicosis, obesity, diabetes, antidiabetic, hypolipidemic, anti-inflammatory, tuberculosis, the polyneuropathy of hereditary transthyretin, and acne." (PMID 37242731, 2023). "Two of the patients without a TTR mutation and one with the V122I mutation had an existing diagnosis of diabetes." (PMID 35959393, 2022). "Our results highlighted a physiological role for TTR in hepatic glucose metabolism and may provide relevant information for the design of TTR-based therapeutic strategies for diabetes and other disorders in which glucose metabolism is impaired." (PMID 34199897, 2021). "In contrast, growth-inhibiting protein 25 (GIG25/AACT/SERPINA3), albumin (ALB), and transthyretin (TTR) were expressed at lower levels in normal patients with abdominal obesity (Group 2), prediabetes (Groups 3 and 4), and diabetes (Groups 5 and 6) than in normal patients (Group 1)." (PMID 31504048, 2019).
diabetes (continued). "Motor impairment was uncommon in patients with diabetes (10/24 TTR‐FAP vs. 1/48 dPNP)." (PMID 29568686, 2018). "TTR expression has also been detected in the urine of diabetes patients." (PMID 23723977, 2013). "Consequently, we first report here that HPβ and TTR may act as a protein biomarker that is specific for diabetes progression in overweight patients." (PMID 31504048, 2019). "We further discovered marked changes in prediabetes/diabetes-related proteins (AACT/SERPINA3, AAT/SERPINA1, ApoA-I, HP, RBP4, TTR, and ZAG)." (PMID 31504048, 2019). "Regulation of TTR and RBP-4 is also interesting given previous relationships between the TTR/RBP-4 complex and diabetes." (PMID 28670222, 2017). "The correlation between aqueous humour TTR levels and diabetes-related cataracts has not been reported." (PMID 37884923, 2023).
Parkinson disease (28 papers, 2010 to 2025). A progressive degenerative disorder of the central nervous system characterized by loss of dopamine producing neurons in the substantia nigra and the presence of Lewy bodies in the substantia nigra and locus coeruleus. "The neuroprotective role of TTR is well established, with evidence of beneficial physiologic activity in AD, Lewy body disorders (such as Parkinson’s disease), and TDP-43–associated neuropathologies." (PMID 40717228, 2025). "TTR has been implicated in several neurodegenerative disorders, such as Parkinson’s disease, which is a Lewy body disorder." (PMID 40717228, 2025). "Over 80 TTR point mutations are related to TTR amyloidogenic behavior and amyloidotic diseases leading to systemic amyloid fibril formation with the characteristic β-sheet cross structure commonly found in several other neurodegenerative disorders such as Alzheimer and Parkinson." (PMID 22053176, 2011). "Tolcapone, an FDA-approved drug for Parkinson’s disease, has been repurposed as a potent and selective TTR stabiliser." (PMID 38203650, 2023). "Tolcapone is another TTR stabilizer approved for clinical use in the treatment of Parkinson’s disease." (PMID 37376074, 2023). "Tolcapone is an FDA-approved drug for Parkinson’s disease that has been repurposed as a TTR stabiliser." (PMID 38203650, 2023). "Sant’Anna and others found that tolcapone, an FDA-approved molecule for Parkinson’s disease, inhibits TTR aggregation and toxicity, binds to TTR in human plasma, and stabilizes the tetramer dissociation in mice and humans." (PMID 35784752, 2022). "These include clinical trials focused on the beneficial effects of TC derivatives (particularly doxycycline and minocycline) on amyloidogenic disorders, including Alzheimer (AD), Parkinson (PD), Huntington (HD) diseases and TTR." (PMID 31546787, 2019). "Here we repurpose tolcapone, an FDA-approved molecule for Parkinson's disease, as a potent TTR aggregation inhibitor." (PMID 26902880, 2016). "Moreover, the importance of TTR stability also concerns neurodegenerative disorders such as Parkinson’s and Alzheimer’s diseases." (PMID 32397334, 2020). "Here the authors show that tolcapone, a drug already FDA-approved for Parkinson disease, has strong transthyretin stabilizing function and might be a superior therapeutic option for CNS amyloidosis as it can cross the blood brain barrier." (PMID 26902880, 2016). "CSF and serum TTR values were neither significantly associated with clinical parameters (age at onset of parkinsonism, duration of parkinsonism, Hoehn&Yahr stage, age at onset of dementia, duration of dementia, MMSE score), nor with ApoE status." (PMID 23133543, 2012).
AA amyloidosis (25 papers, 2015 to 2026). Secondary amyloidosis is a form of amyloidosis, that complicates chronic inflammatory disorders (mainly rheumatoid arthritis) and is characterized by the aggregation and deposition of amyloid fibrils composed of serum amyloid A protein, an acute phase reactant. "The product was compared with99mTc-PYP for cardiac SPECT/CT imaging in a mouse model of AA amyloidosis and for reactivity with human tissue sections from AL and TTR patients." (PMID 38578730, 2024). "A recent study of two affected Abyssinian cats and 195 controls from different breeds concluded a polygenic background of AA-amyloidosis in this breed and found variants in Amyloid Beta Precursor Protein gene (APP) and Transthyretin (TTR) in affected cats." (PMID 38136948, 2023). "The types of CA include the following types: light chain (AL), amyloidosis AA (Amyloid A) and transthyretin (ATTR)." (PMID 34066321, 2021). "APP and TTR are not located within the genomic regions surrounding the significantly AA-amyloidosis-associated SNPs in the present study." (PMID 38136948, 2023). "TTR (Transthyretin) is an amyloidogenic protein and its overexpression in TRAPS patients could be associated with the possible evolution towards AA amyloidosis." (PMID 35812440, 2022). "The material extracted by these solvents has been shown to contain the major amyloid proteins, which characterize the various amyloid types: the 8 kDa amyloid A in AA amyloidosis, the 12–20 kDa light chain fragments in AL, or the TTR monomers (14 kDa) and their fragments in ATTR." (PMID 36902083, 2023).
Cognitive impairment (23 papers, 2011 to 2026). Abnormal cognition is characterized by deficits in thinking, reasoning, or remembering. "We evaluated TTR levels and tetrameric instability in plasma and CSF in mild cognitive impairment (MCI-AD) and Dementia-AD patients examining associations with clinical, biochemical and genetic data." (PMID 41820479, 2026). "The serum concentration of cognitive impairment-linked biomarkers revealed an increase in apolipoprotein A1 (ApoA1) and Transthyretin (TTR) levels in the experimental group at 16 weeks." (PMID 34720860, 2021). "TTR confers neuroprotective properties, and decreased levels of TTR in the cerebrospinal fluid are associated with cognitive impairment." (PMID 30241302, 2018). "From the present results it can be concluded that increased serum concentrations of vitamin A, vitamin D, TTR, albumin, Se and UA could act as a protective factor against cognitive impairment, whereas higher BMI could act as a risk factor." (PMID 35686024, 2022). "Some studies support that reduced TTR levels negatively correlate with disease progression; patients with mild cognitive impairment, which often precedes AD, tend to have higher serum TTR levels, which reduce as the disease progresses." (PMID 40717228, 2025). "Studies have shown that changes in circulating TTR levels track the progression from mild cognitive impairment to dementia in the older population, though not all studies have replicated these findings." (PMID 40717228, 2025). "Tafamidis partially decreased the frequency of TFNEs and contrast enhancement in two patients with the TTR Y69H variant of hereditary ATTR amyloidosis; however, cerebellar ataxia and cognitive impairment gradually progressed." (PMID 40931533, 2025). "PA (also known as transthyretin) is also secreted by the liver and has been widely mentioned in predicting early cognitive deficits in AD and as a target of cognitive interventions." (PMID 35250538, 2022). "Transthyretin in serum, a putative mild cognitive impairment marker, was significantly higher at week 12 in the MHBA group than in the placebo group (p = 0.048)." (PMID 32474473, 2020). "In subjects with mild cognitive impairment (MCI) reduced levels of TTR are detected, with the decrease becoming more pronounced with disease progression." (PMID 33212973, 2020). "In AD patients, plasma TTR levels were significantly lower in AD cases with rapid cognitive decline and with severe cognitive impairment than in those with less rapid decline and less severe impairments." (PMID 31822765, 2019). "Further autopsy studies on patients with TTR meningovascular amyloidosis are necessary to elucidate the significance of tauopathy in the cognitive impairment and to further delineate the neuropathologic changes that underlie dementia." (PMID 26156087, 2015). "Furthermore, reports have identified several other genes, including transthyretin (Ttr), as having potential involvement in depression and cognitive impairment." (PMID 38139000, 2023). "Similarly, transthyretin was identified in AD and mild cognitive impairment CSF62 and in our OPLS-DA analysis; serum amyloid A4 protein contributed to variance in our OPLS-DA analysis; complement component C3, however, was not included on our panel." (PMID 27845782, 2016). "Here, TTR isoforms are profiled directly from CSF by an optimized immunoaffinity-mass spectrometry method in 76 samples from patients with AD (n = 37), mild cognitive impairment (MCI, n = 17)), and normal pressure hydrocephalus (NPH, n = 15), as well as healthy controls (HC, n = 7)." (PMID 24678637, 2014). "TTR has been implicated in dementia, whereby a lack of TTR can exacerbate cognitive impairment." (PMID 35402512, 2022). "Furthermore, it has also been described that TTR-KO mice present memory impairment compared with wild type animals, indicating that the absence of TTR accelerates cognitive deficits usually associated with aging." (PMID 32197355, 2020).
Cognitive impairment (continued). "This is probably due to enhanced expression of NEP and TTR by SUMOylated AICD, resulting in more efficient clearance of Aβ; therefore, less severe pathology and cognitive impairment were observed in APP/PS1 mice." (PMID 32950104, 2021). "Additionally, Sousa and coworkers also described that TTR−/− mice display memory impairment compared with wild-type (TTR+/+) animals, suggesting that the absence of TTR worsens cognitive deficits, a trait that is usually associated with aging." (PMID 33212973, 2020).